SMAD3 (SMAD family member 3)
Diseases named in the same sentence as SMAD3 in open-access papers (continued):
Sharing a sentence is not in itself a finding about the gene and the disease.
kidney disease (46 papers, 2012 to 2025). "Smad3 is regarded as being involved in pathogenic processes by suppressing fibrosis in kidney disease upon Smad3 deletion, such as in DN." (PMID 34122724, 2021). "Smad3 has been recognized as a crucial mediator of TGF-ß biological effects in the fibrogenic process of several renal diseases, since its deficiency in Smad3 knockout mice resulted in suppression of the fibrotic response." (PMID 31455237, 2019). "Indeed, Smad3 has emerged as a key factor that has been tightly linked to matrix accumulation and deletion of Smad3 has been demonstrated to protect against several kidney disease, including AAN." (PMID 28146082, 2017). "We also unexpectedly detected a strong association between the up-regulated genes of the in vitro TGF-β1/Smad3–activated BMDMs with neurogenesis by scRNA-seq in a kidney disease study." (PMID 36206343, 2022). "The current advances in research into the regulation of TGF-β signaling and particularly the Smad3-dependent noncoding RNAs have improved our understanding of the molecular mechanisms of renal inflammation and fibrosis in kidney diseases." (PMID 35541902, 2022). "Smad3-dependent lncRNAs with therapeutic potential in renal diseases have been identified in previous studies." (PMID 35736633, 2022). "TGF-β/Smad3 transits the miRNA profile and promotes renal diseases via regulating transcriptional levels of non-coding RNAs." (PMID 34025445, 2021). "Our findings suggest that targeting Smad3 is a promising therapeutic strategy for the treatment of fibrotic kidney disease under high CRP conditions." (PMID 34671208, 2021). "BMP-7 is a natural antagonist for TGF-β through inhibiting the TGF-β/Smad3, which has been demonstrated on various renal disease models." (PMID 25852569, 2015). "Accumulated evidence shows that targeting Smad3 by overexpressing renal Smad7 produces inhibitory effects on both renal inflammation and fibrosis in a variety of kidney disease models." (PMID 25852569, 2015). "Our laboratory demonstrates that TGF-β/Smad3 signaling is able to regulate the transcription of miR-21, miR-192, miR-433, and the miR-29 family during renal diseases." (PMID 25750628, 2015). "Our laboratory also demonstrates that TGF-β/Smad3 signaling mediates the transcription of miR-21, miR-192, miR-433, and the miR-29 family during renal diseases." (PMID 24550986, 2014). "Disruption of Smad3 diminished UUO-induced renal tubulointerstitial fibrosis, suggesting that Smad3 plays a crucial role in the development of fibrosis in kidney diseases." (PMID 24586712, 2014). "Several studies have investigated the role of Smad2 and Smad3 in the pathogenesis of different renal diseases in vivo." (PMID 24744860, 2013). "However, several experimental models have demonstrated the efficacy of Smad3 inhibition in attenuating kidney disease and ensuing fibrosis in various mouse models, consistent with findings of genetic ablation of Smad3 in different kidney cells." (PMID 39990662, 2025). "Smad3 is the canonical downstream of TGF-β1 signaling, serving as a key mediator of kidney fibrosis by promoting myofibroblast accumulation and fibrogenic molecule production in multiple experimental renal diseases, which is dramatically suppressed by Smad3 deletion." (PMID 35736633, 2022). "PPARα, AMPK, sirtuins, HIF-1, and TGF-β/SMAD3 activation have all been shown to play key roles in the regulation of fatty acid β-oxidation in kidney diseases, and restoration of fatty acid β-oxidation by modulation of these molecules can ameliorate the development of such diseases." (PMID 35517820, 2022). "Thus, targeting Smad3 or its downstream genes specifically related to renal inflammation and fibrosis should provide a novel therapeutic strategy to combat kidney diseases." (PMID 35541902, 2022). "In addition, the new therapeutic approaches for kidney disease by targeting Smad3 signaling, as well as Smad3-dependent microRNAs and lncRNAs are also described." (PMID 35541902, 2022).
kidney disease (continued). "Smad3 is highly activated in a wide range of renal disease; evidence on animal models suggest that the inhibition or blockade of Smad3 may reduce the fibrotic response." (PMID 34054586, 2021). "SMAD3-dependent lncRNAs have been recently uncovered in kidney diseases." (PMID 34025445, 2021). "Deletion of Smad3 has been demonstrated to protect against several kidney disease, including AAN." (PMID 32498221, 2020). "Furthermore, the biological roles of several novel lncRNAs from these 21 Smad3-dependent lncRNAs in kidney diseases were intensively elucidated." (PMID 30287731, 2018). "Besides TGF-β, many mediators, such as advanced glycation end-products and Ang II, can activate Smad3, which acts as a signal integrator in the pathophysiological process leading to kidney disease." (PMID 25148511, 2014). "Basic characteristics of WT and Smad3 KO mice with TGF‐β1‐induced kidney disease." (PMID 24744860, 2013). "Thus, rebalancing Smad3/Smad7 signaling may be a better therapeutic approach for combating kidney diseases." (PMID 35541902, 2022). "Increasing evidence also shows that specifically altering the Smad3-dependent microRNAs or lncRNAs related to fibrogenesis or inflammation locally in the diseased kidney could be a better therapeutic approach for combating kidney disorders." (PMID 35541902, 2022). "Thus rebalancing Smad3/Smad7 signaling by either inhibiting Smad3 and/or activating Smad7 may be a better approach for the development of effective and specific therapy for kidney diseases." (PMID 35541902, 2022). "These novel lncRNAs were Smad3-dependently mediated and may contribute to the renal inflammation and fibrosis in the injured kidneys, which correlated with the progression of experimental kidney diseases in mice." (PMID 30287731, 2018). "Beyond oncology, a VHL-recruiting PROTAC was designed to degrade SMAD family member 3 (Smad3), a key mediator of fibrosis, while stabilizing hypoxia-inducible factor 2 alpha (HIF-2α), a protective factor in kidney disease." (PMID 40507351, 2025). "Thus, specifically targeting Smad3 may be a novel therapeutic approach for kidney diseases." (PMID 35541902, 2022). "In addition, epigenetic identification of Smad3-dependent non-coding RANs that specifically regulate renal inflammation and fibrosis may be the key step forwards the development of effective therapy for kidney diseases." (PMID 35541902, 2022). "In particular, the expression of the pro-fibrotic markers, Smad3, α-SMA, and collagen, was especially enhanced in STZ-treated Nqo1 KO mice, implying the progress of interstitial fibrosis implying leading to end-stage kidney disease." (PMID 33672316, 2021). "This notion is also supported by the results from different mouse models of kidney diseases induced in mice lacking Smad3 or Smad7 or having conditional knockout (KO) for Smad2 or overexpressing renal Smad7." (PMID 24550986, 2014). "To address this, we have employed transgenic mice, with slowly progressing TGF‐β1‐induced kidney disease, with and without an intact Smad3 gene." (PMID 24744860, 2013). "TMAO has been reported to promote cardiac remodeling and renal interstitial fibrosis by activating NF-kB and Smad3, whereas inhibition of TMAO reduces activation of NF-kB and Smad3, preventing cardiac remodeling and renal interstitial fibrosis in multiple cardiac and renal diseases." (PMID 34721039, 2021). "All these studies suggest that specific targeting the downstream TGF-β/Smad3 signaling pathway by overexpression of Smad7, rather than blocking the general effect of TGF-β1 with neutralizing antibodies, may represent a specific and effective therapeutic strategy for kidney disease." (PMID 23301086, 2013).
inflammation (15 papers, 2012 to 2024). Aberrant reaction of the microcirculation characterized by movement of fluid and leukocytes from the blood into extravascular tissues. "Collectively, these results clearly demonstrated that Smad3 deficiency protects against the development of cardiac inflammation in db/db mice." (PMID 33733577, 2021). "We then tested a hypothesis that the protection of Smad3 KO‐db/db mice from cardiac inflammation may be associated with the inactivation of NF‐κB signalling by blocking Smurf2‐mediated ubiquitin degradation of cardiac Smad7." (PMID 33733577, 2021). "Henceforth, TGF-β1/Smad3 targeting appears to be a novel strategy to combat cyclophosphamide-induced renal inflammation and fibrosis." (PMID 37559381, 2023). "Although TGF-β/Smad3 has been considered as a major pathway for fibrogenesis, the diverse roles of this pathway in renal inflammation and fibrosis have hampered the development of anti-TGF-β treatment in general 4-7." (PMID 35541902, 2022). "SP1-TGF-β/Smad3-NFκB-dependent mechanisms have been found to lead to ANG II-mediated renal inflammation and fibrosis in mice." (PMID 36189232, 2022). "Here, we first clarified that miR‐216a induced endothelial senescence and promoted endothelial inflammation via Smad3/IκBα pathway, which thus extended the knowledge on miR‐216a." (PMID 29512862, 2018). "First, Smad3 may exert its chemotactic effect on the macrophage recruitment during renal inflammation as Smad3 can interact with macrophage chemotactic protein-1 (MCP-1) to promote macrophage-dependent renal inflammation." (PMID 35541902, 2022). "Therefore, results from this study suggest that Smad3 may play an essential role in renal inflammation and fibrosis under high CRP conditions." (PMID 34671208, 2021). "In contrast, disruption of Smad3 prevented CRP-exacerbated renal inflammation with sparse F4/80+ cell infiltration and attenuated IL-1β and MCP-1 upregulation as seen in CRP Tg/Smad3 KO mice." (PMID 34671208, 2021). "Interestingly, recent studies also show that deletion of Smad3 from db/db and human CRP transgenic mice can inhibit renal inflammation by blocking MCP-1-dependent macrophage infiltration." (PMID 35541902, 2022).
connective tissue disorder (12 papers, 2013 to 2025). A disease involving the connective tissue. "Our proband’s SMAD3 variant was only detected following a more comprehensive connective tissue disease gene panel." (PMID 31096651, 2019). "Mutations in SMAD3 are linked to Loeys–Dietz Syndrome, an inherited connective tissue disorder." (PMID 40141456, 2025). "Pathogenic heterozygous variants in the SMAD3 gene are a rare cause of connective tissue disorder." (PMID 32154675, 2020). "The consequences of improper TGF-β signaling are reflected in Loeys–Dietz syndrome 3 (LDS3) (OMIM#613795), a multisystem connective tissue disorder caused by pathogenic variants of SMAD3." (PMID 31096651, 2019).
adenocarcinoma (11 papers, 2007 to 2025). A common cancer characterized by the presence of malignant glandular cells. "Elevated SMAD3 mRNA expression has been detected in adenocarcinoma-associated fibroblasts." (PMID 38493128, 2024). "Recently, TGFbeta was shown to induce over-expression of the HCP5 gene and activity of the S-mothers against decapentaplegic homolog 3 (SMAD3) protein complex in adenocarcinomas." (PMID 31137555, 2019). "In the present study, using ALK5 small molecule inhibition and siRNA knockdown of Smad2 and Smad3, we demonstrate that the upregulation of PAR-1 expression is both ALK-5 and Smad3-dependent in A549 adenocarcinoma cells." (PMID 27566553, 2016). "However, knockout of exon 8 in Smad3 results in autoimmunity with abnormally activated T cells, and this induces colon inflammation and adenocarcinomas." (PMID 34966673, 2021). "On the contrary, Smad2 transcript and protein, as well as phosphorylation of SMAD3 and SMAD, remained unchanged in OPN−/−TRAMP NE tumors versus TRAMP adenocarcinomas." (PMID 26700622, 2016). "As protein levels of TGFbRI and TGFbRII were comparable between OPN−/−TRAMP NE tumors and TRAMP adenocarcinoma (not shown), we focused on proteins downstream the TGFβ pathway, particularly Smad2 and Smad3, which are crucial mediators of TGFβ activity in PCa." (PMID 26700622, 2016). "4/5 adenocarcinoma cell lines failed to cell cycle arrest, down-regulate c-Myc or induce p21 in response to TGFβ, and modulation of a Smad3/4 specific promoter was inhibited." (PMID 17264880, 2007). "This evidence together with the reported observation that Smad3 can form transcriptional complexes with Sp1 to regulate gene expression, led us to focus our investigation on Sp1 as a candidate transcription factor in mediating TGFβ-induced PAR-1 upregulation in A549 adenocarcinoma cells." (PMID 27566553, 2016).
cardiovascular diseases (10 papers, 2015 to 2024). "A growing evidence suggests that TGF‐β/Smad3 signalling is a key pathway associated with cardiovascular diseases." (PMID 33733577, 2021). "Of great significance, LEFTY and SMAD3 both play central roles in the Nodal/TGF-βsignaling pathway, with LEFTY negatively regulating the Nodal/TGF signaling pathway and SMAD3 defects being associated with cardiovascular diseases." (PMID 26110764, 2015). "The consequences of Smad3 deletion have been previously examined in several animal models of cardiovascular diseases, but to our knowledge, this is the first evaluation of the role of this transcription factor in cardiac injury by doxorubicin." (PMID 36269647, 2022). "Taken together, accumulating evidence suggests that TGF-β/Smad3 signaling plays an important role in cardiovascular diseases, especially in the pathogenesis of DCM." (PMID 36313337, 2022). "Some of these differences were visualized by mapping the SMAD3 differential gene expression values onto the TCF21 “cardiovascular disease” transcriptional network." (PMID 30307970, 2018).
kidney (9 papers, 2015 to 2023). "The Smad2 and Smad3 are major downstream regulators that promote the TGF-β1-mediated lung fibrosis." (PMID 37580529, 2023). "RSV treatment can significantly activate Sirt1 to suppress Smad3 acetylation and the TGF-β1-induced fibrotic response in the remnant kidney of 5/6 nephrectomized rodents, obstructed kidney model or in cultured cells following TGF-β1 treatment." (PMID 35541902, 2022).
metabolic disease (6 papers, 2014 to 2023). A congenital disorder (due to inherited enzyme abnormality) or acquired (due to failure of a metabolically important organ) disorder resulting from an abnormal metabolic process. "In the early phase after VD, direct disruption of the urethral structure and TGF-β1/Smad3 and Nrf2/ARE signaling inhibition induced a metabolic disorder in the ECM." (PMID 28168411, 2017).
neurodegenerative disease (5 papers, 2015 to 2025). A disorder of the central nervous system characterized by gradual and progressive loss of neural tissue and neurologic function. "Understanding this novel regulatory mechanism provides a deeper insight into the pathological function of PINK1 and SMAD3 in the pathogenesis of neurodegenerative diseases such as PD." (PMID 40064862, 2025). "Finally, we tested SMAD3, another candidate TF from our transposon experiments, and GRN, a secreted growth factor linked to lysosomal function and multiple neurodegenerative diseases." (PMID 41311869, 2025). "In some neurodegenerative diseases, TGF-β1 stimulates the production of inflammatory cytokines such as IL-1β and TNF-via phosphorylation of Smad proteins, including Smad2 and Smad3, in rat neurons." (PMID 37240885, 2023).
cardiac diseases (3 papers, 2015 to 2020). "In the context of fibrosis, Smad3 is pathogenic, which is supported by the finding that mice lacking Smad3 are protected against tissue fibrosis in chronic kidney and cardiac diseases." (PMID 26474462, 2015).
neurological diseases (3 papers, 2013 to 2025). "It has been shown that TGF-β/SMAD3 signaling is associated with several pathological features of neurological diseases, such as dopaminergic neurodegeneration, reduction of dopaminergic axons and dendrites, α-synuclein aggregation, and modulating γ-aminobutyric acid (GABA) neurotransmission." (PMID 37701056, 2023). "Third, the investigation of TGF‐β/Smad3 signaling was confined to the MCAO mouse model, which may limit the generalizability of our findings to other neurological diseases." (PMID 40831324, 2025).
bacterial infection (1 paper, 2016). "Loss of Smad3 has been associated with metastasis in CRC, an outcome that is thought to be dependent on chronic inflammation, e.g., triggered by bacterial infection." (PMID 27092172, 2016).
benign tumors (1 paper, 2015). "Neoplastic cells in benign tumors showed high levels of phosphorylated Smad3, indicative of high TGFβ signaling activities." (PMID 25885043, 2015).
brain disorder (1 paper, 2023). A disease affecting the brain or part of the brain. "Furthermore, deficiencies in TGF-β/SMAD3 signaling may represent a risk factor for the development of some brain disorders." (PMID 37701056, 2023).
infectious disease (1 paper, 2019). A disorder directly resulting from the presence and activity of a microbial, viral, or parasitic agent in humans. "The analysis in CD34+ cells highlighted mechanisms related to SUMOylation of chromatin organization proteins, infectious disease, transcriptional activity of SMAD2/SMAD3 and cellular responses to stress." (PMID 31546608, 2019).
psychiatric disease (1 paper, 2022). "This miRNA has not been thoroughly studied in the context of psychiatric disease; the current literature does suggest it has a significant role in promoting neuronal apoptosis in the context of ischemia by targeting BRI3 and SMAD3 mRNA." (PMID 36217923, 2022).
respiratory disease (1 paper, 2021). "This information suggesting that under-expressed SMAD3 in CoV mediated respiratory disease has a prospective role in the pathogenesis of SARS-CoV-2." (PMID 33968364, 2021).
vasculopathies (1 paper, 2014). "Similar to other conditions known as TGF-β vasculopathies (MFS, which is caused by FBN1 mutations and LDS, which is caused by TGFBR1, TGFBR2, SMAD3 and TGFB2 mutations), the SLC2A10 loss of function activates the TGF-β signaling pathway." (PMID 25373504, 2014).
SMAD3 also shares sentences with these, for which no sentence is quoted: acute myeloid leukemia (6 papers); nonalcoholic steatohepatitis (5); Parkinsonism (5); vascular Ehlers-Danlos syndrome (5); allergic disease (4); Aneurysm - osteoarthritis syndrome (4); atrial fibrillation (4); dilatation (4); acute lymphoblastic leukemia (3); cutaneous melanoma (3); gastric tumor (3); Lewis lung carcinoma (3); osteonecrosis (3); amyotrophic lateral sclerosis (2); aortic insufficiency (2); Aortic root aneurysm (2); atrial septal defect (2); cancers of the digestive system (2); colon (2); hypertrophy (2); hypophysitis (2); immune dysfunctions (2); intervertebral disc degeneration (2); intestinal cancer (2); intracranial aneurysm (2); Knee Osteoarthritis (2); left ventricular hypertrophy (2); lupus nephritis (2); mitral valve prolapse (2); myositis (2).
A further 127 diseases each share a sentence with SMAD3 in 2 papers or fewer.